TMEM39A (transmembrane protein 39A)
Description:
Regulates autophagy by controlling the spatial distribution and levels of the intracellular phosphatidylinositol 4-phosphate (PtdIns(4)P) pools. Modulates (PtdIns(4)P) levels by regulating the ER-to-Golgi trafficking of the phosphatidylinositide phosphatase SACM1L. (Microbial infection) Positively regulates the replication of encephalomyocarditis virus (EMCV) via autophagy-dependent pathway.
Synonyms: SUSR2; FLJ10902
Tractability: Antibody: UniProt predicts a signal peptide or a membrane-spanning region. PROTAC: ubiquitination databases record sites on it.
Gene: Protein-coding gene on chromosome 3 (119,428,949 to 119,468,854, reverse strand). Ensembl gene ENSG00000176142.
Subcellular location: Endoplasmic reticulum membrane
Subcellular location (Human Protein Atlas): Nucleoplasm; Vesicles
Gene Ontology:
Molecular function: protein binding
Biological process: negative regulation of autophagosome assembly; negative regulation of autophagosome maturation; positive regulation of viral genome replication
Cellular component: endoplasmic reticulum membrane
Genetic constraint (gnomAD): Loss-of-function variants: 19 observed, 48.08 expected, observed/expected ratio (o/e) 0.4, 90% interval 0.28 to 0.58. The upper end of that interval is the gene's LOEUF score, 0.58, which puts it in group 2 of 6, group 1 being the genes least tolerant of losing a copy. Missense variants: 430 observed, 613.69 expected, observed/expected ratio (o/e) 0.7, 90% interval 0.65 to 0.76. Synonymous variants: 197 observed, 230.35 expected, observed/expected ratio (o/e) 0.86, 90% interval 0.76 to 0.96.
Homologues: Orthologues: chimpanzee TMEM39A (100% identical), macaque TMEM39A (99% identical), pig TMEM39A (99% identical), dog TMEM39A (99% identical), guinea pig TMEM39A (99% identical), rabbit TMEM39A (98% identical), mouse Tmem39a (95% identical), rat Tmem39a (92% identical), tropical clawed frog tmem39a (86% identical), zebrafish tmem39a (70% identical), Caenorhabditis elegans tmem-39 (27% identical), Drosophila melanogaster CG13016 (27% identical). Paralogues in human: TMEM39B (51% identical).
Diseases named in the same sentence as TMEM39A in open-access papers:
TMEM39A is named in the same sentence as 9 diseases in open-access papers, as found by Europe PMC text mining. Sharing a sentence is not in itself a finding about the gene and the disease. The quoted sentences say what the papers report.
autoimmune disease (4 papers, 2009 to 2021). A disorder resulting from loss of function or tissue destruction of an organ or multiple organs, arising from humoral or cellular immune responses of the individual to their own tissue constituents. "TMEM39A is a susceptibility locus associated with various autoimmune diseases and highly up-regulated in brain tumors." (PMID 33524011, 2021). "TMEM39A is known to be associated with autoimmune diseases, such as systemic lupus erythematosus and multiple sclerosis." (PMID 31849860, 2019). "However, GWS studies have implicated TMEM39A in lupus, an autoimmune disease characterized with dysfunctional IFN responses." (PMID 31849860, 2019). "It has been reported to be associated with autoimmune diseases, glioma, and other cancers; however, knowledge regarding the biological function of TMEM39A remains limited." (PMID 31849860, 2019). "Our findings provide novel ideas for clarifying the role of TMEM39A in the process of viral infection and clinical therapy of certain autoimmune diseases and cancers related to TMEM39A." (PMID 31849860, 2019). "To date, almost no biological data of TMEM39A have been reported and only two SNPs in TMEM39A were identified as being associated with the susceptibility of autoimmune diseases." (PMID 28427360, 2017). "IRF8, TMEM39A and IKZF3-ZPBP2 were previously identified as susceptibility loci for SLE in the multiracial replication study, Besides, ORMDL3 and GSDMB were found to have susceptibility loci for autoimmune diseases." (PMID 28427360, 2017).
multiple sclerosis (4 papers, 2015 to 2021). A progressive autoimmune disorder affecting the central nervous system resulting in demyelination. "In recent GWAS, a genetic variant on TMEM39A was discovered and replicated as an important risk locus for multiple sclerosis, an autoimmune condition of the central nervous system." (PMID 33902726, 2021). "The results of the study performed by IMSGC, presenting TMEM39A (3q13.33) as potential MS susceptibility locus (International Multiple Sclerosis Genetics C 2010) prompted us to investigate this gene in well-defined Polish population." (PMID 28444502, 2017). "Although very limited biological data of TMEM39A is published so far, its polymorphisms have been found to be associated with multiple sclerosis and SLE." (PMID 28427360, 2017). "TMEM39A rs1132200 have been found to be associated with susceptibilities to multiple sclerosis and SLE in multiracial replication study." (PMID 28427360, 2017). "In our study, we concentrated on the transmembrane protein 39A gene (TMEM39A), which was found to be associated with MS susceptibility in GWAS performed by International Multiple Sclerosis Genetics Consortium (IMSGC) (International Multiple Sclerosis Genetics C, 2010)." (PMID 28444502, 2017). "Our investigation is the first which indicates that TMEM39A mRNA expression may be associated with the development and/or course of multiple sclerosis." (PMID 28444502, 2017). "The goal of this study was to confirm and understand the potential role of one of such genes—transmembrane protein 39A gene (TMEM39A)—in multiple sclerosis." (PMID 28444502, 2017). "At 3q13.33, a coding SNP (rs1132200) in TMEM39A has been reported to be associated with both SLE and multiple sclerosis." (PMID 25890262, 2015). "Since, to date, very little is known about TMEM39A gene, it is hard to predict what role it may play with regard to multiple sclerosis." (PMID 28444502, 2017). "In conclusion, although we were not able to find the association of TMEM39A polymorphisms with predisposition to multiple sclerosis and course of the disease, we showed that its mRNA expression is decreased in PBMC of MS patients." (PMID 28444502, 2017).
lupus (2 papers, 2017 to 2019). "This study aimed to assess the association between 14 single nucleotide polymorphisms (SNPs) in six genes (IRF8, TMEM39A, IKZF3, ORMDL3, GSDMB, and ZPBP2) and systemic lupus erythematosus (SLE) in a Chinese Han population sample." (PMID 28427360, 2017).
glioma (1 paper, 2019). A benign or malignant brain and spinal cord tumor that arises from glial cells (astrocytes, oligodendrocytes, ependymal cells). "Furthermore, TMEM39A has been proposed to be a novel marker for the diagnosis of glioma and other tumors." (PMID 31849860, 2019).
optic neuritis (1 paper, 2013). Optic neuritis is inflammation of the optic nerve, the nerve that carries the visual signal from the eye to the brain.The conditionmay cause sudden, reduced vision in the affected eye(s). "There were trends for associations of the TMEM39A and MPHOSPH9 polymorphisms with reduced odds of optic neuritis as well." (PMID 24130718, 2013).
viral infection (1 paper, 2019). "This is the first study to clarify the role of TMEM39A in viral infection and provide evidence of a relationship with autophagy pathway." (PMID 31849860, 2019). "This is the first study to clarify the role of TMEM39A in viral infection and also hints that there may be a interplay between TMEM39A and the ATG7-dependent autophagy pathway." (PMID 31849860, 2019). "Our findings provide novel ideas for clarifying the role of TMEM39A in viral infections." (PMID 31849860, 2019).
infection (2 papers, 2017 to 2019). The state of being infected such as from the introduction of a foreign agent such as serum, vaccine, antigenic substance or organism. "Future work investigating EMCV infection in host primary cells is crucial as this would allow us to pin point the exact transcriptional timing of TMEM39A regulation." (PMID 31849860, 2019). "We showed that EMCV GS01 strain infection upregulated TMEM39A expression." (PMID 31849860, 2019). "Since the expression levels of TMEM39A were significantly upregulated and EMCV GS01 strain infection could induce complete autophagy in different cells, we speculate that TMEM39A may play a positive regulatory role in the proliferation of EMCV relying on autophagic signaling." (PMID 31849860, 2019). "Thus, we speculate that the upregulation of TMEM39A expression by EMCV may be related to the role of TMEM39A interaction with VP2; however, the effect of the interaction of VP1 and TMEM39A on EMCV infection is not yet known." (PMID 31849860, 2019).
TMEM39A also shares sentences with these, for which no sentence is quoted: brain tumors (1 paper); cancer (1).